INS (insulin)
Diseases named in the same sentence as INS in open-access papers (continued):
Sharing a sentence is not in itself a finding about the gene and the disease.
type 2 diabetes (continued). "If the cost of producing autologous iPS cells and differentiating each individual line into functional islets can be reduced, providing autologous SC-islets to insulin-dependent individuals with type 2 diabetes may also be feasible." (PMID 33454830, 2021). "Moreover, this opens therapeutic perspectives for the potential applications of CM-derived proteins/peptides especially in type-2 diabetes and insulin resistance situations where insulin's action needs to be corrected and improved." (PMID 35223937, 2021). "Thus, a detailed understanding of ER stress and insulin dysfunction’s etiology can help find a novel treatment for type II diabetes." (PMID 34299638, 2021). "Additionally, administration of WHPs in streptozotocin-induced type 2 diabetic mice resulted in a reduction of fasting glucose level and increase in insulin secretion." (PMID 34445765, 2021). "Metformin is a first-choice treatment for type 2 diabetes and may be administered to acromegalic patients to reduce glycemia and improve insulin sensitivity." (PMID 34884872, 2021). "Furthermore, MSM improves glucose tolerance and insulin sensitivity in mouse models of obesity and type 2 diabetes." (PMID 34684621, 2021). "Type 2 diabetes is characterized by an insulin resistence and hiperinsulinemia." (PMID 33672318, 2021). "Type 2 diabetes begins with a progressive decline of insulin action." (PMID 34299261, 2021). "Therefore, strategies to control obesity have direct applications in enhancing insulin sensitivity and deferring the onset or progression of type 2 diabetes." (PMID 33959308, 2021). "When dietary measures and oral glucose lowering drugs (OGLDs) fail to sufficiently correct glucose dysregulation, most treatment guidelines for type 2 diabetes (T2DM) advise to start or add either an injectable glucagon‐like peptide‐1 analogue or insulin therapy." (PMID 33855214, 2021). "Insulin infusion could suppress the CCL4 expression in mononuclear cells from patients with type 2 diabetes." (PMID 33968046, 2021). "Thus, insulin dysfunction is initiated, resulting in chronic hyperglycemia with the consequences of developing type II diabetes." (PMID 34299638, 2021). "Insulin administered in this way appears to improve the potential of the brain’s mitochondrial membrane and stimulates the activity of the brain’s mitochondrial complexes in a streptozotocin-induced model of early type 2 diabetes." (PMID 33921992, 2021). "In the study of type 2 diabetes, 5 studies detailed records of insulin decline." (PMID 33957998, 2021). "Tweeters with type 2 diabetes actively tried to avoid starting insulin." (PMID 33496671, 2021). "The application of Epac2 agonists might be helpful for the treatment of type 2 diabetes with impaired insulin release from pancreatic β-cells." (PMID 33714195, 2021). "In another randomized crossover trial, substituting red meat with legumes (lentils, chickpeas, peas, and beans) significantly decreased fasting blood glucose, insulin, and the triglyceride level in patients with diabetes type-2, suggesting the potential role of plant-based proteins over animals." (PMID 35118103, 2021). "Insulin treatment has been associated with elevated risk for incident or recurrent MACE in patients with type 2 diabetes without or with established, stable atherosclerotic cardiovascular disease." (PMID 34158057, 2021). "In another study, NO-nitrite-nitrate plasma levels wereanalyzed, and it was found that these are affected by aging, smoking habits,pregnancy, menopause, thyroid hormones and pathologies such as: type II diabetes,resistance to insulin, hypertension and kidney dysfunction." (PMID 34617949, 2021). "Similarly, leptin therapy only produces modest effects on insulin sensitivity in type 2 diabetes due to leptin resistance." (PMID 33935782, 2021). "Research investigating the premise of the fetal insulin hypothesis will continue to be important as type 2 diabetes becomes more prevalent globally." (PMID 33569631, 2021).
type 2 diabetes (continued). "Protein exhibits the strongest genetic correlations with poor health outcomes, including obesity (rg = 0.35, SE = 0.04), type 2 diabetes (rg = 0.45, SE = 0.06), fasting insulin (rg = 0.41, SE = 0.08), and coronary artery disease (rg = 0.16, SE = 0.04), as well as BMI (rg = 0.40, SE = 0.04)." (PMID 32393786, 2021). "The top five pathways by association for Whites were linoleic acid with FAD1 (26.0%) and FAD2 (67.5%), regulation of insulin secretion with insulin (88.7%), type 2 diabetes with insulin (78.5%), pancreatic secretion with insulin (70.9%), and fatty acid elongation with FAD1 (38.8%) and FAD2 (60.1%)." (PMID 33933074, 2021). "This study confirmed an inverse correlation of DR with C peptide and insulin in type 2 diabetes." (PMID 34912295, 2021). "Type 2 diabetes is considered to have a chronic low-grade inflammation state, and the increase of inflammatory factors may affect insulin signal transduction, which is related to the formation of insulin resistance." (PMID 33510802, 2021). "Another cross-sectional study that enrolled elderly in-patients with type 2 diabetes who received insulin therapy showed that daytime and pre-midnight mean glucose levels were reliable markers to identify patients with an increased risk of nocturnal hypoglycemia." (PMID 33794984, 2021). "An alternative explanation (the fetal insulin hypothesis) was put forward in 1998, proposing that lower birthweight and adult-onset type 2 diabetes are two phenotypes of the same genotype." (PMID 33569631, 2021). "Given that skeletal muscle is a major site for glucose disposal, quantitative declines in muscle volume in patients with type 2 diabetes might adversely affect overall glucose metabolism; thus, insulin therapy could improve optimal glucose targets." (PMID 34203830, 2021). "This provides powerful new information illustrating that in type 2 diabetes, endogenous insulin and/or C-peptide secretion, when it fails, may be responsible for development or progression of DR." (PMID 34912295, 2021). "A recent study evaluated its effect in type 2 diabetes and revealed that Rg1 increased glucose uptake in chronic insulin-treated muscle cells, concomitant with the activation of AMPK, suggesting that activation is required for the improvement of insulin sensitivity in these cells." (PMID 34836306, 2021). "We have earlier, in several steps, developed mathematical models for insulin signalling in human adipocytes: first in isolation and later connected to models of systemic glucose control, and used the models to unravel key alterations in type 2 diabetes." (PMID 34972146, 2021). "The study further advances our knowledge of the downstream signaling events that may be targeted to restore insulin secretion regulation in β-cells defective in leptin signaling, such as those from obese individuals with type 2 diabetes." (PMID 33617875, 2021). "PPARγ activation has a robust insulin sensitizing effect, making TZDs potent insulin sensitizers and highly effective oral medications for type 2 diabetes, although, their clinical use is limited by major adverse effects including weight gain, fluid retention, and osteoporosis." (PMID 34966295, 2021). "According to the obtained results, we concluded that long-term swimming training and receiving P. psyllium simultaneously improved memory deficit and insulin sensitivity in streptozotocin–nicotinamide-induced type 2 diabetic rats through the amelioration of lipid profile." (PMID 34837961, 2021). "The huge differences in mouse serum insulin levels suggest that deletion of Smad3 may have an impact on islet beta cells in type 2 diabetes." (PMID 33456576, 2021). "Hence, it is of interest to show the mechanism of action of β-Caryophyllene on insulin signalling molecules in gastrocnemius muscle of high fat diet - induced type-2 diabetic rats." (PMID 35540699, 2021).
type 2 diabetes (continued). "Type 1 diabetes (aOR 0.35, 95%CI:0.27 to 0.45, p < .001), type 2 diabetes (aOR 0.74, 95%CI:0.59 to 0.93, p < .05) and gestational diabetes treated with Insulin (aOR 0.83, 95%CI:0.78 to 0.87, p < .001), decreased the odds of SGA compared to women without these conditions." (PMID 34051749, 2021). "Intriguingly, although variation in TCF7L2 has been identified as the strongest common genetic determinant of type 2 diabetes, it was not a significant determinant of beta-cell glucose sensitivity but was associated with the early insulin response to an IVGTT." (PMID 32944759, 2021). "Recent evidence indicates that 5‐HT weight loss medications also directly improve type 2 diabetes without weight loss by reducing hepatic glucose production and increasing insulin sensitivity." (PMID 33909316, 2021). "Physical training improves insulin sensitivity and can prevent type 2 diabetes (T2D)." (PMID 34943951, 2021). "When ER stress occurs in a cell that results in sorcin (a Ca2+-binding protein that helps to maintain Ca2+ homeostasis in ER) dysfunction, it also increases the ATF6 activity, which results in the advancement of insulin dysfunction, obesity, and type II diabetes." (PMID 34299638, 2021). "Type II Diabetes Mellitus (T2D), the most common endocrine disorder, is a chronic metabolic disease characterized by insulin resistance and eventual inability of the pancreas to secrete insulin, resulting in hyperglycemia that over time damages body tissues such as nerves and blood vessels." (PMID 34439295, 2021). "Insulin-induced vasodilation of resistance arteries, i.e. vascular insulin sensitivity, and fatty acid uptake are two interrelated endothelial functions that contribute to the pathophysiology of type 2 diabetes." (PMID 34214082, 2021). "However, patients with type 2 diabetes treated with OGLDs plus insulin or insulin alone were more likely to have microalbuminuria than those with type 1 diabetes." (PMID 33594476, 2021). "Since then, oats have been shown to improve insulin sensitivity, glucose metabolism, blood lipid profile, endothelial function and inflammation, all important markers associated with the development of type 2 diabetes (T2D), cardiovascular disease (CVD) and all-cause mortality." (PMID 34444718, 2021). "Protein-tyrosine phosphatase 1B (PTP1B) negatively regulates insulin signaling pathways and plays an important role in type 2 diabetes mellitus (T2DM), as its overexpression may induce insulin resistance." (PMID 33557071, 2021). "Indeed, propolis extracts have been depicted to restore glucose tolerance and insulin sensitivity/secretion in several type 2 diabetes animal models." (PMID 33803136, 2021). "However, it is very difficult to separate the systemic effects of hyperglycaemia, reduced insulin secretion (type-1 diabetes) or reduced insulin sensitivity (type-2 diabetes), from any putative direct protective effects of insulin on pancreatic acinar cells." (PMID 34282152, 2021). "Chromium administration may be a crucial adjunct therapy for type 2 diabetes because it may be involved in glucose metabolism through potentiating insulin’s actions." (PMID 34564583, 2021). "It is common to treat type 2 diabetes by regular injections of insulin." (PMID 35111536, 2021). "Meal replacement-based lifestyle interventions should therefore not only be used in the treatment of manifested type-2-diabetes but also in primary prevention, while insulin measurements might be used to monitor for compliance in carbohydrate restriction." (PMID 33922802, 2021). "Adults with type 1 diabetes showed slightly more optimal medication intake and fewer perceived barriers than adults with non-insulin-treated type 2 diabetes and showed slightly more optimal medication intake behavior than adults with both insulin-treated and non-insulin-treated type 2 diabetes." (PMID 36994341, 2021).
type 2 diabetes (continued). "Gene Expression Omnibus (GEO) datasets (GSE27951, GSE55200, and GSE26637) of insulin-resistant individuals or type 2 diabetes patients and normal controls were downloaded to get differently expressed genes (DEGs), and GO and KEGG pathway analyses were performed." (PMID 33564304, 2021). "In type 2 diabetes, ER stress also plays an important role due to the fact that a synthesis of insulin occurs in the ER of the pancreatic islet and an increase in insulin production could place a strain on ER function, resulting in an activation of the UPR." (PMID 33800427, 2021). "In patients with type 2 diabetes, hypoglycaemia may also occur, particularly with insulin or sulfonylurea treatment." (PMID 33672913, 2021). "This opens the possibility that (early) interventions able to normalize/reduce plasma insulin concentrations might play a key role in the prevention and treatment of obesity, type 2 diabetes, cardiovascular disease, cancer and premature mortality." (PMID 34360563, 2021). "Therefore, for the first time, the present study was designed to evaluate the possible ameliorative effects of swimming training and P. psyllium on the cognitive malfunction, insulin sensitivity, and lipid profile in type 2 diabetic rats." (PMID 34837961, 2021). "While alpha and beta endocrine cells are stimulated to release glucagon and insulin, respectively, discordance in both cell types has been shown to increase disease pathogenesis in type 1 and type 2 diabetes." (PMID 32270277, 2020). "The combination of high insulin and glucose levels is critical to the development of type 2 diabetes; however, why starved animals have high insulin levels and how exactly glucose and other hormones impact tumor cell proliferation in starved animals still requires further investigation." (PMID 32857726, 2020). "In pre-marketing trials, patients treated with TI were more likely to discontinue participation compared with those treated with an active comparator (29.5% for TI versus 15.3% for subcutaneous insulin or oral anti-diabetic drugs) for both type-I and people with type-II diabetes." (PMID 32785196, 2020). "However, one of several options recommended in the German guidelines for the treatment of patients with diabetes type 2 is adding basal insulin at bedtime to metformin (basal supported oral therapy, BOT)." (PMID 32316649, 2020). "However, pregnant women with type 2 diabetes who showed normal glycemia and HbA1c were still on insulin treatment during almost 3.4 ± 2.1 years of duration of disease." (PMID 32626786, 2020). "Similarly, post-load insulin levels during a glucose tolerance test predict the development of type 2 diabetes, as insulin release is pulsatile, resulting in oscillating ultradian periodicity." (PMID 31552570, 2020). "This study indicated that post-meal walking of at least one meal per day might be as efficient as one mealtime insulin to improve glycemic control in type 2 diabetic patients who failed from basal insulin therapy." (PMID 32236116, 2020). "These neural pathways could be modulated to regulate the secretion of insulin and glucagon in patients with type 2 diabetes and early stages of type 1 diabetes, where there are still a considerable number of β-cells intact." (PMID 32467827, 2020). "For patients with type 2 diabetes before chemotherapy, insulin substitution therapy is recommended." (PMID 31876135, 2020). "This suggests that this continuous exposure affects the metabolism of insulin, including FBG and HbA1c, and may be a risk factor for the development of metabolic diseases such as glucose intolerance or type 2 diabetes later in life." (PMID 32552747, 2020). "As plasma pH is slightly reduced in type 2 diabetic patients and we have previously shown that plasma CTSD activity is causally linked to insulin levels in vivo, it is likely that the activity of CTSD in plasma will be increased in type 2 diabetes compared to healthy individuals." (PMID 33101209, 2020).
type 2 diabetes (continued). "In addition, for individuals who have type 2 diabetes and short sleep duration, those using both insulin treatment and oral glucose-lowering medication have poorer sleep quality, such as obstructive sleep apnoea." (PMID 32671413, 2020). "We investigated whether dulaglutide (DU)‐combined conventional insulin therapy is beneficial for glycemic control in non‐critically ill hospitalized patients with type 2 diabetes." (PMID 31168938, 2020). "Therefore the aim of this study was to elucidate insulin injection techniques, treatment satisfaction and glycemic control after education among patients with type 2 diabetes in large cohort of polish population." (PMID 32071879, 2020). "Hepatic lipid accumulation may facilitate resistance to both insulin and glucagon, which are important pathophysiological characteristics of type 2 diabetes." (PMID 33488526, 2020). "Additionally, resistance exercise training also increases muscle insulin sensitivity in older type 2 diabetes adults." (PMID 33003389, 2020). "A small cluster of microbes or their metabolites may be targeted for mitigating defects in insulin clearance and hyperinsulinemia during the progression of obesity and type 2 diabetes." (PMID 32860984, 2020). "Maternal diabetes implied, on top of obesity, an additional increased risk for offspring to receive any ICD-10 F code diagnosis, with the pointwise effect size generally larger in the order insulin-treated pregestational diabetes first, then type 2 diabetes, and then gestational diabetes." (PMID 32031649, 2020). "In conclusion, although post-meal walking might be as effective as one prandial insulin to improve glycemic control in type 2 diabetic patients who failed basal insulin but the magnitude of reduction was small." (PMID 32236116, 2020). "In turn, the contribution of vitamin D to the pathogenesis of type-2 diabetes is not fully understood, although the localization of vitamin D receptors on pancreatic beta cells demonstrates the potential role for insulin secretion, thereby maintaining glucose levels." (PMID 32143350, 2020). "Our findings indicate that suppression of Aurora-A could at least partially enhance insulin sensitivity by decreasing the number of infiltrating macrophages and IL-6 level in a type 2 diabetic mouse model." (PMID 33043822, 2020). "Select members of the gut microbiota or their components and metabolites may be a target for mitigating defects in insulin clearance, which may be relevant to cumulative insulin load and the progression of obesity and type 2 diabetes." (PMID 32860984, 2020). "Inflammation is a primary event in Type 1 diabetes where infectious (viral) and/or autoimmune processes initiate disease; in contrast, chronic inflammation is typical in Type 2 diabetes and is considered a sequel to increasing insulin resistance and disturbed glucose metabolism." (PMID 33240272, 2020). "We performed a cross-sectional chart review study utilizing the electronic database of the Third Affiliated Hospital of Sun Yat-sen University, and included 257 patients with type 2 diabetes undergoing intensive insulin therapy in the Department of Endocrinology and Metabolism." (PMID 33015194, 2020). "Our analysis indicates these findings apply to those with type 1 and type 2 diabetes, whether treated on diet alone, oral agents, insulin, or a combination of treatments, as well as those with prediabetes." (PMID 32142510, 2020). "Of these 173 patients, 87 were randomized to the glyburide group: 4 patients were excluded from the trial (type 2 diabetes, pharmacotherapy unnecessary, lost to follow-up, treatment refused), and 18 patients were switched to insulin treatment due to inadequate blood glucose control." (PMID 32379777, 2020). "For the prediction of type 2 diabetes, we investigated DNA methylation at cg06500161 and cg05639842 with common risk factors for type 2 diabetes (fasting blood glucose and insulin levels) in non-diabetic participants in both cohorts." (PMID 32612641, 2020).